EGFR (epidermal growth factor receptor)
Diseases named in the same sentence as EGFR in open-access papers (continued):
Sharing a sentence is not in itself a finding about the gene and the disease.
tumor (continued). "In both tumour cell lines, DNA FISH demonstrated that EGFR-high cells had a significantly higher number of EGFR DNA foci than EGFR-low." (PMID 36476408, 2022). "Currently, an IdyllaTM system for circulating tumor DNA in blood samples have already been developed for BRAF, KRAS, NRAS, and EGFR." (PMID 35474548, 2022). "Among the 34 enrolled patients, one patient exhibited focal EGFR and KRAS amplification, which occurred concurrently in progressive tumor cells." (PMID 35883645, 2022). "We note this hypothesis leads to a clinical prediction: the large size of the conserved EGFR-mut interactome is consistent with clinical observations that targeted therapy blocking the EGFR-mut oncogenic signal profoundly decreases the fitness of individual tumor cells." (PMID 36612014, 2022). "Several studies assessed the correlation of radiolabeled cetuximab uptake with EGFR expression to predict response to anti-EGFR therapies in HNSCC, showing a clear tumor visualization in almost all patients (8/9) in phase I clinical trial." (PMID 35836956, 2022). "In an analysis of a tumor cell/immune cell mixture, a clean separation between tumor (HER2+/EpCAM+/MUC1+/EGFR+) and immune cells (CD45+) was observed." (PMID 35508767, 2022). "Epithelial cell adhesion molecules (EpCAM) CD133, EGFR, and HER2 are additional targets overexpressed in cancer cells, cancer stem cells, and/or tumor endothelial cells, which have been exploited in the design of aptamer-functionalized nanoparticles." (PMID 35626078, 2022). "The results demonstrate that the expression of EGFR, IGF1, PTGS2, FGF1, CAV1, and PLCB1 were significantly different (p < 0.01) in PABC tissues as compared to non-tumor tissues, with a similar pattern to that observed in the microarray analysis." (PMID 36035177, 2022). "The proliferative type is mainly characterized by excessive activation of cell proliferation-related signaling pathways such as RAS/MAPK, MET, EGFR, ERBB2, and NOTCH; therefore, the tumor is more aggressive." (PMID 36578029, 2022). "the combination of EGFR-TKI and tumor resection provided better PFS and OS than EGFR-TKI alone, and patients who underwent tumor resection within six months had fewer co-existing genomic alterations and better PFS." (PMID 36581631, 2022). "Overexpression of EGFR and HER3 can activate HER2 cell signaling pathways (such as PI3K) and lead to tumor proliferation." (PMID 35142964, 2022). "In the EGFR-mutant brain metastatic animal model of NSCLC, a significant decrease in tumor volume was observed in AZD3759 treated mice." (PMID 34738874, 2022). "Previous studies have shown that simultaneous targeting of EGFR, HER2, and HER3 with multispecific antibodies can prevent compensatory tumor promoting mechanisms within the HER family, providing a scientific rationale for the development of a pan-HER antibody." (PMID 36703993, 2022). "Mechanistically, hCAP18/LL-37 promotes the release of HB-EGF, upregulates the phosphorylation of EGFR/HER2, activates the PI3K/Akt signaling pathway, and promotes HCC cells proliferation and tumor growth." (PMID 35039485, 2022). "Lowering the affinity of the Fab to the antigen also has the added advantage of increasing the specificity to antigens that are significantly overexpressed on tumor tissues (eg, HER2/EGFR)." (PMID 35728874, 2022). "The targeting of the EGFR signaling pathway was found to decrease the repair capacity of DNA double-strand break (DSB), the most deleterious type of DNA damage, in tumor cells." (PMID 35453686, 2022). "Using IB and IHC staining, we also observed that the levels of EGFR, p-AKT, and p-STAT3 were down-regulated in FBXW2-overexpressing tumor tissues of mice model, whereas p21 and p27 were enhanced." (PMID 35499593, 2022).
tumor (continued). "We found that the expression levels of EGFR and CXCR4 in serum sEVs correlated well with the IHC staining results of the primary tumor tissue for the four patients." (PMID 35269297, 2022). "For targeting receptor kinase signaling pathways including EGFR, HER2, HER3, and MET in tumor cells, GBR1302 has been developed as a T-cell engager to direct CD3-positive T cells to HER2 on tumor cells." (PMID 36432687, 2022). "The same authors found that EGFR and EGFRvIII interact with pro-apoptotic protein PUMA, preventing its translocation on mitochondria and increasing aggressiveness of the tumor." (PMID 36551529, 2022). "Cetuximab exhibits its antitumor activity by inhibiting EGFR-mediated tumor growth and stimulating NK-cell-mediated antibody-dependent cellular cytotoxicity (ADCC) activity to lyse tumor cells." (PMID 35890277, 2022). "Our results demonstrate positive co-expression of PDGF and VEGFR2 or EGFR in tumor tissues from early (UICC stage I and II) and advanced (UICC stage III) stage patients (PDGF: Cy3, red; VEGFR2 and EGFR: Alexa 488, green)." (PMID 36264073, 2022). "In the current study, treatment by the combination of RU.521 and EGFR inhibitors (afatinib or gefitinib) on two independent PDTOs supports the tumor-suppressing activity of co-inhibition of the cGAS-STING and EGFR pathways." (PMID 35992877, 2022). "After combining JHU083 with EVax, a peptide vaccine that specifically targets wildtype regions of the EGFR protein, the inhibitory rate increased to around 54%, indicating JHU083 enhanced the anti‐tumor efficacy of EVax." (PMID 35861366, 2022). "EGFR entering the nucleus can promote the expression of c-myc, cyclin D1, and PTGS2, and can contribute to tumor cell proliferation." (PMID 35603146, 2022). "By modulating epidermal growth factor (EGFR) activation, SPP1 can influence the immune escape and malignant biological activity of tumor cells, and its overexpression enhances HCC development and metastasis." (PMID 36353638, 2022). "The EGFR monoclonal antibody BK011 and cetuximab inhibited tumor growth in the GCPDX model with EGFR amplification." (PMID 35664756, 2022). "EGFR and PI3K/Akt pathway inhibitors or combinations thereof can induce an autophagic response in tumor cells." (PMID 36551613, 2022). "Consistently with the notion that dual inhibition of EGFR and AMPK signaling in HCC827 xenografts led to metabolic crisis and eventually tumor cell death." (PMID 37192859, 2022). "In EGFR-mutant NSCLC, EGFR signaling plays an important role in tumor invasion activity by regulating hypoxia-independent hypoxia inducible factor-1α (HIF-1α) and vascular endothelial growth factor (VEGF) expression." (PMID 35935943, 2022). "Upon review of additional tumor gene subpopulations, APC gene status was identified as a key prognostic indicator of EGFR-inhibitor efficacy." (PMID 35685436, 2022). "The most common EGFR deletion is EGFRvIII, which lacks exons 2–7 in the extracellular domain and is found in as much as 66% of GBM tumours with amplified EGFR." (PMID 36497413, 2022). "Macropinocytosis is induced by the activation of various receptors, such as the epidermal growth factor receptor (EGFR), which is highly expressed in tumour cells, such as human epidermal cancer A431 and the chemokine receptor CXCR4." (PMID 36361760, 2022). "EGFR or ALK status data were available for 82 patients (86.3%), and PD-L1 tumor expression data were available for 76 patients (80.0%)." (PMID 35130287, 2022). "Treatment has been based on widely expressed antigens across tumor types such as HER2, EGFR, and GD2." (PMID 35844304, 2022). "A study showed that the level of immunosuppressive cells and immune checkpoint proteins increases during the EGFR-TKI resistance period, implicating a critical mechanism for tumor progression." (PMID 35806042, 2022).
tumor (continued). "The upregulation of EGFR has been reported in liver macrophages in both human and animal HCC models, where it functions as a tumor promoter." (PMID 35628212, 2022). "Beyond the prediction of EGFR-TKI resistance, upregulated LINC00460 in tumor specimens was correlated with worse PFS and OS (p = 0.046 and 0.014, respectively)." (PMID 36139582, 2022). "EGFR, a well-described transmembrane protein, is a member of ERBB receptor tyrosine kinase superfamily which promotes tumor cell migration." (PMID 34991461, 2022). "These poor outcomes have been attributed to the lower levels of PD-1 molecule expression on EGFR mutant NSCLC cancer cells and to the complex interactions of EGFR mutant cells with the tumor microenvironment (TME)." (PMID 35884398, 2022). "Taken together, the tumour antigens MSLN, CD70, EGFR and HER2 are being exploited as targets for target‐selective CD47 blockade for solid cancer with preclinical proof‐of‐concept for enhanced selectivity and activity." (PMID 35908284, 2022). "CXCR7/Src/EGFR-mediated miyogenic signaling is negatively regulated by ARRB2, a tumor suppressor, which plays a crucial role in controlling CXCR7/EGFR-mediated tumor cell proliferation." (PMID 36276080, 2022). "We administered paclitaxel on day −1, and EGFR-TRAB on day 0, then the MKN45 tumour was collected on day 6 for RNA analysis." (PMID 36071036, 2022). "More importantly, COX-2 is a mediator of angiogenesis and tumor growth through upregulation of vascular endothelial growth factor (VEGF) and of epidermal growth factor receptor (EGFR), respectively." (PMID 35203404, 2022). "Here, our discussion will focus on persistent activation of the EGFR/K-RAS/MAPK/SIAH pathway, which drives chemo-resistance, early tumor relapse, and high mortality in TNBC." (PMID 36176751, 2022). "Briefly, TMEM16A positively correlates with epidermal growth factor receptor (EGFR) expression in tumor development, and both TMEM16A and EGFR are found in NSCLC tissues." (PMID 35205604, 2022). "The pharmacological mechanism of cetuximab is its unique role as an antibody against epidermal growth factor receptor (EGFR), which also plays an important role in tumor metabolism." (PMID 36111743, 2022). "Three tumour cells A549, MCF-7, PC-3 and EGFR kinase were employed to evaluate their biological activities." (PMID 36176072, 2022). "The epidermal growth factor receptor (EGFR) pathway is also crucial in cancers for it encourages metastasis and tumor growth." (PMID 36362345, 2022). "EGFR and GFAP were predominantly expressed by tumor cells, often at varying levels, with expression of both proteins highest in EGFR-amplified tumors, consistent with the AC-like differentiation of these tumors." (PMID 35973991, 2022). "For VCAM1, EGFR and CD24 our findings were validated with healthy and tumor tissue data obtained from the Human Protein Atlas." (PMID 36221114, 2022). "The hybrid molecule, originally called EGFATF-PE, and later EGFR-targeted bispecific angiotoxin (eBAT), consists of human EGF, human ATF and a modified Pseudomonas (PE) toxin which induces tumor killing at pico-molar concentrations." (PMID 35158766, 2022). "In this study, to represent the molecular heterogeneity characterizing this tumor, we used U87MG, and the same ones engineered to over-express wild type (wt) EGFR or EGFRvIII and primary GBM patients-derived cells." (PMID 36551529, 2022). "The epidermal growth factor receptor (EGFR) and its downstream signaling pathways, including the RAS-RAF-MAPK and phosphatidylinositol 3-kinase (PI3K)-Akt pathways, play important roles in tumor growth in CRC." (PMID 35474548, 2022). "Similar to TCTP WT, TCTP S46D transfection into A375 P0 cells led to the activation of the EGFR-AKT signaling pathway, and promoted the immune-refractory properties of the tumor cells." (PMID 35440620, 2022). "It is observed that by knocking it out, EGFR/AKT survival signaling, and tumor growth are inhibited." (PMID 35955786, 2022).
tumor (continued). "The phosphorylation process marks the activation of the EGFR/PI3K signalling pathway, and the abnormal activation of this pathway plays a key role in the occurrence and development of tumours." (PMID 36090016, 2022). "Factors significantly prognostic for OS in the GSE72094 dataset included risk score based on the four autophagy-immune-related genes, as well as patient gender and tumor TNM stage, KRAS status, and EGFR status." (PMID 36177001, 2022). "In EGFR mutant NSCLC cell lines, the treatment with statins was shown to augment the anti-tumor effects of ACLY inhibition; this effect was attributed to the inhibition of PI3K/AKT and MAPK pathways." (PMID 35159223, 2022). "boulardii can inactivate epidermal growth factor receptor (EFR), which can further suppress EGFR-Erk and EGFR-Akt pathways resulting in induced apoptosis in tumor cells and reducing the level of cell colony formation and cancer cell proliferation." (PMID 35628700, 2022). "All these studies suggest the potential of miR-125 as a therapeutic target in EGFR- and/or HER2-positive tumor types, such as GC." (PMID 36145507, 2022). "In conclusion, our study revealed that the combination of EGFR-TKI and tumor resection provided better PFS and OS than EGFR-TKI alone." (PMID 36581631, 2022). "Eight hub genes (CDK1, EGFR, UBC, MYC, CCNB1, RHOB, CDC6, and CDC20) have tumor suppressor functions, while five hub genes (CDK1, EGFR, FYN, UBC, and CCNB1) are protein kinases as well." (PMID 35632527, 2022). "We recently reported opposing roles for EGFR signalling between HPV-negative and positive HNSCC, where in the latter EGFR was a positive prognostic marker, delaying tumour cell proliferation and inhibiting DNA damage repair leading to radiosensitivity." (PMID 36333293, 2022). "EGCG inhibits growth factors, e.g., EGFR and IGFR-1 and their signaling pathways, which suppresses a growth of tumor cells and metastasis." (PMID 36613784, 2022). "Recent research has revealed potential epigenetic-transcriptional mechanisms by which tumor cells remodel their TIME and suggested EGFR inhibitors as potential immunotherapy sensitizers in PAAD53." (PMID 35831362, 2022). "Intrinsic tumor subtypes were determined using both PAM50- and IHC-based detection of estrogen receptor, progesterone receptor, Ki-67, epidermal growth factor receptor, and cytokeratins 14 and 5/6." (PMID 35568835, 2022). "Erlotinib is a TKI capable of inhibiting EGFR, and patients with NSCLC show tumour response, survival and tumour‐related symptom improvement, whereas its efficacy is limited by inevitable drug resistance developed in long‐term treatment." (PMID 35605028, 2022). "M2 macrophages secrete EGF to activate tumor cell EGFR and upregulate the VEGF/VEGFR signaling pathway to promote tumor cell proliferation and migration." (PMID 36532066, 2022). "R-PTP-κ is a tumor suppressor that dephosphorylates and inactivates oncogenic proteins such as STAT3, EGFR and CD133." (PMID 36551956, 2022). "Because synovial hyperplasia and pannus formation which invades cartilage and bone leading to joint destruction is similar to a tumor with its neovascularization and cellular infiltration, involvement of EGF and EGFR in RA pathology has been proposed." (PMID 36326383, 2022). "EGFR is highly expressed in ESCA and some other cancer types; moreover, it is seen as a promising target for inhibiting tumor aggression." (PMID 35069736, 2022). "Assuming that the driver mutations in genes such as EGFR, ALK, ROS1, HER2, and MET (among others) had demonstrated advantages favoring cell transformation, leading to the expansion of the altered clone, which could be followed by tumor formation and its evolution." (PMID 36430388, 2022). "We first compared the expression pattern of EGFR, ERBB2, ERBB3, ERBB4 in CESC tumor and normal tissues." (PMID 35581263, 2022). "More specifically, high EGFR expression is related to maintaining a highly proliferative, astrocytic-like state in GBM tumour cells." (PMID 36497413, 2022).
tumor (continued). "The in vivo silencing of GOLPH3, in a combinatorial anti-tumor therapy, by using GOLPH3 siRNA and Gefitinib both conjugated to nanoparticles, inhibited EGFR signalling and glioma growth in the mouse model." (PMID 35465326, 2022). "Cetuximab (CTX), an epidermal growth factor receptor (EGFR) monoclonal antibody (mAb), can negatively regulate tumour growth and induce an efficient antitumour effect." (PMID 34976187, 2022). "MAP kinase, Estrogen, EGFR, TGFbeta and WNT signaling activity was significantly decreased in HPV-positive compared to HPV-negative tumours." (PMID 35954409, 2022). "The EVs secreted by tumor cells within the tumor microenvironment transfer angiogenic factors such as EGFR and VEGF into ECs, inducing a pro-angiogenic niche to support the pathological angiogenesis and tumor growth." (PMID 36358833, 2022). "In the electron transfer-triggered images, the afterglow signals of cetuximab-treated tumor tissues were apparently weaker than those of the PBS-treated group, revealing the inhibition of EGFR in the cetuximab-treated group." (PMID 35105871, 2022). "This strong CAR T cell expansion came to an end after day 13, aligning with a plateau of the anti-tumor effect in EGFR CAR T cell treated animals between day 16 and day 20, indicating an end of the active tumor-killing phase." (PMID 35836798, 2022). "Hence, a combined EGFR/CD3 expression profile could potentially be used to make important treatment related decisions for EGFR+ patients that typically have an increased likelihood of tumor recurrence and progression." (PMID 35957892, 2022). "MET amplification mediates resistance to EGFR-TKI by activating ERBB3 signaling to activate phosphatidylinositol 3-kinase, thus providing a bypass mechanism of tumor growth." (PMID 34953403, 2022). "Moreover, a previous study found that PD-1 inhibitors are less effective in treating NSCLC patients with EGFR mutations, and low levels of both programmed death-ligand 1 (PD-L1) and CD8+tumor infiltrating lymphocytes in the TME might be the basis of this adverse clinical response." (PMID 35154456, 2022). "An in-depth analysis of the tumor composition displayed a compliant expression pattern between EGFR and the epithelial marker CD326, whose levels decreased upon EGFR CAR T cell+IL-2 treatment indicating the highest tumor cell death in this cohort." (PMID 35836798, 2022). "One clinical study used a cocktail of CAR T therapies in patients with terminal CCA with the sequential infusion of epidermal growth factor receptor (EGFR)-specific and CD133-specific CAR T cells, which effectively inhibited tumor progression." (PMID 36341440, 2022). "A UniCAR system targeting EGFR and CD98 through the use of two TMs was shown to significantly reduce the tumour growth of these radioresistant cells in vivo." (PMID 35205725, 2022). "The majority of the biomarkers examined in this analysis are involved in tumor cell proliferation, HER2, EGFR, cyclin D, KI67 and MTOR were among the most frequently reported in literature found by the authors." (PMID 35246597, 2022). "Blocking all activated RTKs, including AXL, PDGFRα, EGFR and HER2, is required to further impair tumor growth with MEKi 121, suggesting functional redundancy of these RTKs in PDAC." (PMID 35966590, 2022). "Epidermal growth factor receptor (EGFR) is a prototypical receptor tyrosine kinase that is overexpressed in HNSCC and affects the proliferation, apoptosis, angiogenesis, and metastasis of tumor cells." (PMID 36092724, 2022). "EGFR pathway is present in most of NSCLC and leads to the continuous increase of the tumor through angiogenesis, invasion, metastasis and inhibition of apoptosis." (PMID 35599008, 2022). "As previously observed in vitro, pladienolide B administration in vivo significantly decreased various relevant tumor progression markers and critical oncogenic spliceosome components (VEGFA/EGFR/CDK4/PDGFRA/PDGFRB and SRSF3/PTBP1)." (PMID 35086552, 2022).